EPHA1 (EPH receptor A1)
Diseases named in the same sentence as EPHA1 in open-access papers (continued):
Sharing a sentence is not in itself a finding about the gene and the disease.
psychosis (2 papers, 2024 to 2026). "BIN1 and EPHA1 have been linked to psychosis, whereas NME8 has been inversely associated with apathy." (PMID 38473892, 2024). "The genetic variant EPHA1*C has also been related to MBI psychosis." (PMID 38473892, 2024). "The Apolipoprotein E (APOE) genotype and the MS4A locus have been associated with affective dysregulation, ZCWPW1 with social inappropriateness and psychosis, BIN1 and EPHA1 with psychosis, and NME8 with apathy." (PMID 38473892, 2024). "Associations with APOE and MS4A for affective dysregulation, ZCWPW1, EPHA1, and BIN1 for psychosis-related symptoms, and NME8 for apathy highlight the possibility that MBI domains represent clinically observable phenotypes of underlying genetic susceptibilities." (PMID 41591092, 2026).
breast tumors (1 paper, 2023). "Analogous to our observation that high EPHA1 expression in PCa was associated with worse patient survival, high EPHA8 expression in breast tumors has been associated with poor patient prognosis." (PMID 36806315, 2023).
colorectal tumors (1 paper, 2014). "Conversely, elevated levels of EPHA1 were observed in early stage compared to late stage colorectal tumors." (PMID 25193853, 2014). "Point mutations in EPHA2 and EPHA1 have not been specifically described in the literature for primary colorectal tumors, and lower mutation frequencies for these genes (4.4% EPHA1 and 2.6% EPHA2) were reported for primary colorectal tumors in the TCGA database." (PMID 25193853, 2014).
Hypercholesterolemia (1 paper, 2013). An increased concentration of cholesterol in the blood. "Among the highly up-regulated genes in the MCA of the hypertension plus hypercholesterolemia group compared to sham controls were EPHA1, SP110, SLFN14." (PMID 23874591, 2013). "Of the DEGs in the MCA that were up-regulated in the hypertension plus hypercholesterolemia group vs. sham controls on a normal diet, EPHA1 had the largest fold change, followed by SP110, and SLFN14." (PMID 23874591, 2013).
lung adenocarcinoma (1 paper, 2014). A carcinoma that arises from the lung and is characterized by the presence of malignant glandular epithelial cells. "Moderate/high EphA1, A4, A5 and A7 expression was more frequently observed in lung adenocarcinoma patients with ECOG performance status < 2 compared to those with ECOG performance status ≥ 2, at a non significant level (p > 0.05, data not shown)." (PMID 24495444, 2014).
medulloblastoma (1 paper, 2025). A malignant, invasive embryonal neoplasm arising from the cerebellum. "EphA1 expression is reduced in medulloblastoma cell lines (DAOY, Res-220, Res-256, Uw-426, Uw-473, Uw-402) compared to normal fetal brain and adult cerebellum." (PMID 41200151, 2025).
Ovarian cyst (1 paper, 2006). The presence of one or more cysts of the ovary. "Hence EphA1, EphA2, EphB2, EphB3, EphB6, ephrin A1, ephrin A5 and ephrin B1 were selected for further analysis in an additional fourteen tumor samples, one ovarian cyst and one ovarian adenoma." (PMID 16737551, 2006).
Parkinson disease (1 paper, 2024). A progressive degenerative disorder of the central nervous system characterized by loss of dopamine producing neurons in the substantia nigra and the presence of Lewy bodies in the substantia nigra and locus coeruleus. "Another study linked increased EPHA1 expression to increased neuroinflammation in a neuronal SH-SY5Y cell culture model of Parkinson’s disease as well as in the substantia nigra of a mouse Parkinson’s disease model, but the effects of EPHA1 mutations were not examined." (PMID 39706267, 2024).
sarcoma (1 paper, 2019). A usually aggressive malignant neoplasm of the soft tissue or bone. "Among the genes that are downregulated in sarcoma in all three species, there are three known tumor suppressors: TP63, EPHA1, and DUSP26 (which may alternately function as an oncogene depending on the cancer context)." (PMID 30947707, 2019).
schizophrenia (1 paper, 2019). A major psychotic disorder characterized by abnormalities in the perception or expression of reality. "We examined expression of known GPI-APs previously associated with schizophrenia, GPC1, NCAM1, MDGA2, and EPHA1." (PMID 30664618, 2019). "To investigate the potential consequences of a deficit in export and/or quality control, we measured cell membrane-associated expression of known GPI-APs that have been previously implicated in schizophrenia, including GPC1, NCAM, MDGA2, and EPHA1, using Triton X-114 phase separation." (PMID 30664618, 2019).
systemic lupus erythematosus (1 paper, 2021). An autoimmune multi-organ disease typically associated with vasculopathy and autoantibody production. "The remaining variants rs56402156, rs7920721, and rs4351014 (in/near EPHA1, ECHDC3, and HS3ST1) have not been directly associated with other traits, although their associated genes were implicated in systemic lupus erythematosus (HS3ST1) and cancer (EPHA1, ECHDC3)." (PMID 34992629, 2021).
uveal melanoma (1 paper, 2020). A melanoma derived from melanocytes of the uveal tract. "Analysis of the results of this study showed that in uveal melanomas, high expression of EphA1 is associated with lower mitotic activity, smaller tumor size, less frequent extra-scleral infiltration, and less frequent loss of chromosome 3." (PMID 33007931, 2020). "The aim of the study was to evaluate the expression of ephrin receptors EphA1, EphA5, and EphA7 in uveal melanoma and its associations with clinicopathological parameters, overall survival, and disease-free survival." (PMID 33007931, 2020). "The present study documented for the first time that some uveal melanomas express EphA1, EphA5, and EphA7 receptors." (PMID 33007931, 2020). "The present study aimed to assess EphA1, EphA5, and EphA7 expression in uveal melanoma, combined with clinicopathological parameters, overall survival, and disease-free survival." (PMID 33007931, 2020). "In uveal melanoma, as with EphA1, high EphA5 expression is also a favorable prognostic factor." (PMID 33007931, 2020).
vitreous hemorrhage (1 paper, 2020). Blood extravasation in the vitreous humor. "High expression of EphA1 was positively correlated with a smaller tumor size, less frequent extra-scleral extension, lower mitotic activity, and more frequent vitreous hemorrhage." (PMID 33007931, 2020).
cancer (38 papers, 2006 to 2025). A tumor composed of atypical neoplastic, often pleomorphic cells that invade other tissues. "Both genes encode proteins that are linked to cancer hallmarks—Epha1 is an ephrin receptor subfamily of the protein-tyrosine kinase family and Wnt7b is a WNT family member." (PMID 34398873, 2021). "EphA1 and ephrinA1 are up or downregulated in several malignant tumors, such as advanced skin cancer and colorectal cancer." (PMID 39839790, 2024). "A few cancers or cancer-related genes [such as EPHA1 (OMIM*179610), MGLL (OMIM*609699), DLG1 (OMIM*601014), SLC49A4 (OMIM *602773)] have also been observed." (PMID 38540211, 2024). "FCS measurements were performed on live cancer cells with stable expression of GFP-tagged EphA2 mutation constructs (DU145), and mouse epithelial tumor cells with EphA1/EphA2 gene knockout and stable expression of GFP-tagged EphA2 mutation constructs." (PMID 28338017, 2017). "Historically, the first Eph receptor, EphA1 and its Eph receptor-interacting (ephrin) ligand, ephrin-A1, were cloned from cancer cells." (PMID 24098442, 2013). "EphA1, originally isolated as an amplified gene in a carcinoma cell line, is preferentially expressed in epithelial cells." (PMID 19277044, 2009). "Among the Eph receptors, EphA1 has received comparatively less attention in human cancer research." (PMID 38651144, 2024). "Other data indicate that EPHA1 may play different roles during the different stages of cancer progression." (PMID 31412533, 2019). "In fact, the first Eph receptor (EphA1) and the first ephrine (ephrin-A1) were both identified as tumor antigens from carcinoma cell lines, and their overexpression could lead to oncogenic transformation in NIH3T3 fibroblasts." (PMID 26989075, 2016). "Among fellow RTKs, EPHA1, EPHA2, FGFR2, PDGFRß, Ret, and VEGFR2 have often been linked to cancer." (PMID 26073592, 2015). "Therefore, although the level of EphA1 expression in human cancer cells used in this study is very low, it is essential to characterize whether the serine residue of EphA1 is a substrate for RSK or Akt." (PMID 26158630, 2015). "Finally, EPHA1, the first member of the erythropoietin-producing hepatocellular (Eph) family of receptor tyrosine kinases, was recently shown to potentially play a role in carcinogenesis and the progression of several cancer types." (PMID 25390635, 2014). "In our dataset, in addition to EPHB1, we also identified EPHA1, EPHA2 and EPHA7 that were highly phosphorylated in cancer compared to normal tissue, making these proteins as potential therapeutic targets." (PMID 36093296, 2022). "There were some RTK genes (EPHB6, EPHA1, EPHB3, FGFR4, PDGFRB, and FLT4) showing amplification in cancer cells." (PMID 32038722, 2019). "While the expression of EphA1 and EphA2 increases in early stages of CRC, the abundance of these receptors decreases in advanced stages of the cancer." (PMID 29682554, 2018). "Ephrin A5 does not bind significantly to EphA1 but has been shown to activate EphA2 in human carcinoma cells." (PMID 16737551, 2006). "In contrast, EphA1 and EphA5 demonstrated a distinct negative correlation (Correlation coefficient =−0.36), suggesting intricate co-expression interactions involving numerous EphA genes across diverse cancer types." (PMID 38952552, 2024). "EPHA1 and EPHA2 proteins expression, although lower in cancer tissues compared with matched non-malignant ones, was observed as higher in metastatic lesions than in primary tumor specimens." (PMID 34445116, 2021).
tumor (35 papers, 2006 to 2025). "EPHA1 overexpression was associated with high tumor proliferative capacity, assessed by the Ki67 index, probably revealing a link between its upregulation with more aggressive tumor phenotypes." (PMID 34445116, 2021). "EphA1, A5 and A7 expression were positively associated with tumor proliferative capacity (p = 0.047, p = 0.002 and p = 0.046, respectively)." (PMID 24495444, 2014). "Elevated EphA1, A4, A5 and A7 expression was also associated with increased tumor proliferative capacity." (PMID 24495444, 2014). "A positive EPHA1 and EPHA2 protein staining as well as a low EFNA1 protein level were significantly linked to more aggressive tumor features, but only a positive EPHA1 immunoreactivity was significantly associated with poor survival." (PMID 25025847, 2014). "EphA1 staining intensity was significantly associated with tumor size and histopathological stage." (PMID 39839790, 2024). "EphA1/A2 and EphrinA1 were implicated in tumor angiogenesis in the bladder." (PMID 35770949, 2023). "Interestingly, ARID1B1 and BRCA2 mutations were found to be SVZM+ tumor exclusive by deep NGS of the Heidelberg cohort as well as EPHA1, DECAF12L2, and ADCY5 by WES in the TCGA cohort." (PMID 35660939, 2022). "Moreover, positive staining of both EPHs was associated with aggressive tumor features, while positive EPHA1 staining was also linked to poor patient OS." (PMID 34445116, 2021). "The total high expression of EphA1 was statistically associated with smaller tumor size (p = 0.048), less frequently occurring extra-scleral infiltration (p = 0.030), lower mitotic activity (p = 0.042), and more frequent presence of hemorrhage in the vitreous chamber (p = 0.014)." (PMID 33007931, 2020). "Immature DCs have a strong migration ability and canbe recruited to tumor sites through the presentation of DAMPs suchas EphA1 and mature ubiquitin antigens." (PMID 39739571, 2025). "The IHC expression of EphA1, A2, A4, A5, and A7 and the staining intensity were evaluated in tumor samples from 67 patients with PDAC." (PMID 39839790, 2024). "EEFNA1 encodes EPH protein and is involved in regulating developmental events, while EPHA2 can interact with EPHA1 to regulate the movement and proliferation of tumor cells." (PMID 39256364, 2024). "Further, we revealed that the increased expression of EphA1 in HCC cells led to an increased SDF-1 concentration in the tumor microenvironment, which in turn activated the SDF-1/CXCR4 axis and enhanced the recruitment of EPCs to HCC." (PMID 27066828, 2016). "Our previous study also found that the targeted suppression of EphA1 expression significantly inhibited the tumor growth of HCC xenografts, mainly by suppressing tumor angiogenesis." (PMID 27066828, 2016). "By manipulating the expression of EphA1 in xenografted tumor tissue and in cultured HCC cells, we observed that the up-regulation of EphA1 expression in HCC cells promotes the chemotaxis of EPCs to tumors and endothelial cells through a paracrine mechanism." (PMID 27066828, 2016). "In this study, the Boyden chamber assays showed that the chemotaxis of EPCs to the ECs and tumor cells was significantly enhanced in the conditioned medium from HLE cell cultures with activated EphA1." (PMID 27066828, 2016). "Previous studies have reported an elevated expression level of EphA1 and its analogue, EphA2, in the tumor tissue of HCC patients." (PMID 27066828, 2016). "Here, for the first time, we observed that the SDF-1/CXCR4 axis can be activated by the increased expression of EphA1 in HCC cells in the tumor microenvironment." (PMID 27066828, 2016). "Further, both in vivo and in vitro experiments confirmed the pivotal role of the SDF-1/CXCR4 axis in mediating the promotive effect of EphA1 on EPCs’ homing to tumor neovasculature." (PMID 27066828, 2016). "The ephrinA1/EphA1 pathway was also found to be involved in the malignant biological behavior of HCC tumor cells." (PMID 27066828, 2016).
tumor (continued). "In this study, the activation of the ephrinA1/EphA1 signaling pathway in HCC cells led to an elevated SDF-1 protein level in the HCC tumor microenvironment." (PMID 27066828, 2016). "To date, functional reports on characterizing the role of EPHA1 in tumor angiogenesis are still missing." (PMID 25025847, 2014). "In support of this notion, patients with low EphA1 expressing tumours had significantly shorter survival than the high EphA1 group." (PMID 19277044, 2009). "In seeking to understand this biphasic expression pattern, we found that reduced EphA1 expression was more frequent in late-stage CRCs (stage III vs stage II), suggesting that there was a selective loss of expression during tumour progression." (PMID 19277044, 2009). "Again, heterogeneous EphA1 expression was observed, with 2- to 10-fold upregulation compared with paired normal colon in 52% of tumours." (PMID 19277044, 2009). "In line with that pathophysiology, several Ephs and ephrins, including EphA1, EphA2, EphA3, EphA4, EphB2, EphB3, and ephrin-A1, are overexpressed in a variety of tumors, and exhibit mostly tumor-promoting properties." (PMID 18648668, 2008). "Notably, EphA1 and EphA2 exhibited heightened expression in the C1 and C2 subtypes, indicating a plausible involvement in tumor promotion." (PMID 38952552, 2024). "Furthermore, the knockout EphA1 from GC cell lines reduced invasiveness in vivo showing a potential role in tumor progression." (PMID 39839790, 2024). "EPHA1: EPHA1 is overexpressed in various human tumor types including HCC." (PMID 37444544, 2023). "In addition, the canine limb tumor was imbedded in skeletal muscle, allowing us to compare expression of EphA1 in RMS and skeletal muscle directly." (PMID 36214254, 2022). "While the mouse cell lines were derived from transgenic mice with RMS-causing mutations, the replication of our results in human patient-derived cell lines and canine primary tumor samples indicates that nuclear localization of EphA1 is a broad property of RMS cells." (PMID 36214254, 2022). "EFNA1 could also interact with ephrin receptor EPHA1, which is overexpressed in PTC and then associates with tumor growth, invasiveness, and metastasis, to trigger transcription factor PDX1, which is modified by phosphorylation to cause its activation." (PMID 31126066, 2019). "Moreover, targeting SDF-1 with siRNA suppressed the ephrinA1/EphA1-enhanced potential of EPCs to migrate to the tumor cells." (PMID 27066828, 2016). "In addition, compared with SDF-1 scrambled RNA, the SDF-1 siRNA-treated HLE cells with activated EphA1 expression showed remarkably smaller resulting tumors (c1), suggesting a pivotal role of SDF-1 in EphA1-enhanced tumor growth." (PMID 27066828, 2016). "Our previous study also showed that the targeted inhibition of EphA1 could inhibit tumor growth and angiogenesis in HCC." (PMID 27066828, 2016). "In this study, we found that the up-regulation of EphA1 expression in HCC cells could affect not only the chemotaxis of EPCs to tumor cells and endothelial cells (ECs) but also the tube formation ability of EPCs in a paracrine fashion." (PMID 27066828, 2016). "This suggests that the role of EPHA1 in tumorigenesis and metastasis depends on the tumor entity." (PMID 25025847, 2014). "In summary, most Eph receptors (EphA1, EphA2, EphA3, EphA4, EphA5, and EphA7) function as promoters of GC progression, influencing metastasis, tumor invasion, angiogenesis, and drug resistance, while EphA1 has a more complex role depending on tumor differentiation." (PMID 39839790, 2024). "One could speculate that tumor cells with an “aggressive” expression status, i.e. over-expression of EPHA1 and EPHA2 as well as down-regulation of EFNA1, possess a survival advantage under adverse conditions and thus, are capable of thriving in the foreign microenvironment of secondary sites." (PMID 25025847, 2014).
tumor (continued). "In summary, suppression of EphA1 in models of HCC resulted in reduced proliferation, motility, and invasion of tumor cells." (PMID 39839790, 2024). "In tumor-to-stroma signaling, primary and metastatic lesions are characterized by EFNA2 interacting with EPHA1, EFNB3 interacting with EPHB2, and EFNB3 interacting with EPHB6, among several others." (PMID 36676129, 2023). "The results revealed that compared with the SDF-1 scrambled RNA-transfected cells with activated EphA1 expression, the HCC xenografts derived from SDF-1 siRNA-knockdown HLE cells had a smaller number of EPC cells homing to the tumor vasculature (Fig. 6d2)." (PMID 27066828, 2016). "An abnormal expression of EPHA1, EPHA2 and EFNA1 with influence on patient outcome has been demonstrated in different tumor entities." (PMID 25025847, 2014). "Nevertheless, inhibition of EPHA1 and EPHA2 resulted in reduced tumor growth and invasiveness in various oncogenic animal models." (PMID 25025847, 2014). "Through a siRNA library screening that targeted most genes encoding RTKs and subsequent validation, we found that knockdown of 4 RTK receptors (FGFR2, RON, EPHA1, and RYK) via siRNA sensitized MET-addicted tumor cells to PF, while b-FGF-induced activation of FGFR2 conferred resistance to the PF." (PMID 26528757, 2015). "EphA1 expression was independent of age, gender, tumour type and grade, although overall survival was marginally better in women compared to men (P<0.05)." (PMID 19277044, 2009). "In 22/24 tumor samples, EphA1 expression was more than five times the level seen in non-malignant controls." (PMID 16737551, 2006). "How EPHA1 acts is not definitely elucidated, but the ratio of EPH receptors to ligands is thought to be an important determinant of tumor progression." (PMID 25025847, 2014).